IFNL4 (interferon lambda 4 (gene/pseudogene))
Description:
Cytokine that may trigger an antiviral response activating the JAK-STAT pathway and up-regulating specifically some interferon-stimulated genes.
Synonyms: IFNAN
Gene: Protein-coding gene on chromosome 19 (39,246,314 to 39,248,856, reverse strand). Ensembl gene ENSG00000272395.
Subcellular location: Cytoplasm; Secreted
Genetic constraint (gnomAD): Missense variants: 271 observed, 195.04 expected, observed/expected ratio (o/e) 1.39, 90% interval 1.26 to 1.54. Synonymous variants: 112 observed, 83.61 expected, observed/expected ratio (o/e) 1.34, 90% interval 1.15 to 1.57.
Diseases named in the same sentence as IFNL4 in open-access papers:
IFNL4 is named in the same sentence as 41 diseases in open-access papers, as found by Europe PMC text mining. Sharing a sentence is not in itself a finding about the gene and the disease. The quoted sentences say what the papers report.
hepatitis C (15 papers, 2013 to 2024). "Since the discovery of the polymorphic nature of the IFNL4 gene, its variants have been investigated and associated with several viral diseases, with an emphasis on hepatitis C. However, the impacts of these variants on mixed-race and native populations in the northern region of Brazil are scarce." (PMID 38003018, 2023). "Polymorphisms in the interferon lambda gene locus (IFNL) such as the IFNL4 genetic variants rs12979860 and rs368234815 are predictive of resolution of hepatitis C virus infection, but information about the impact of these variants in other infections is scarce." (PMID 31637221, 2019). "In the various patient groups in this study, IFNL4 transcripts were exclusively detected in liver specimens from patients with hepatitis C, in fact in 24/45 (53.3%) of the samples." (PMID 24376784, 2013). "In this regard, induction of IFNL4 mRNA in hepatitis C liver tissue is surprising as it is apparently the only IFN in the liver shown to date to be clearly inducible by HCV infection in humans." (PMID 24376784, 2013). "Here we report on a first cross-sectional analysis of IFNL4 gene transcripts in liver biopsies from patients with hepatitis C, hepatitis B, various inflammatory liver diseases due to other etiologies, and from patients without any histological liver disease." (PMID 24376784, 2013). "The authors demonstrated slightly higher IFNL2/IFNL3 mRNA expression in the liver of hepatitis C patients carrying the minor non-favorable IFNL4 rs12979860 C alleles." (PMID 26606750, 2015). "Alternatively, the new hepatitis C therapies such as sofosbuvir, ledipasvir, and daclatasvir, which are not known to be affected by the mutations in IFNL3 and IFNL4 genes, can be used." (PMID 36388934, 2022). "Comparing hepatitis C with non-hepatitis C patients, rs12979860 as well as IFNL4 ss469415590 genotype distributions were significantly different with a higher minor allele frequency among hepatitis C patients." (PMID 24376784, 2013). "Although IFNL4 polymorphisms are important predicators of hepatitis C cure with interferon-based therapies, newer DAA therapies are interferon-free, and as such IFNL4 polymorphism assessment will not be as useful in countries where only DAAs are being used to treat HCV." (PMID 36689413, 2023). "The mechanism by which the IFNL4 locus affects hepatitis C outcomes has not been fully elucidated." (PMID 29534310, 2018). "A common variant rs368234815TT/∆G creating functional gene from an IFNL4 pseudogene is associated with the expression of major ISGs in the liver but impaired clearance of hepatitis C. To explain this, we compared Halo-tagged and non-tagged IFNL3 and IFNL4 signaling in liver-derived cell lines." (PMID 33806448, 2021).
COVID-19 (14 papers, 2021 to 2025). A disease caused by infection with severe acute respiratory syndrome coronavirus 2. "We also demonstrated that the presence of the T/T genotype and the T allele for IFNL4 were significantly associated with increased mortality in COVID-19 patients." (PMID 38703289, 2024). "We analyzed the genotype frequencies of IFNL4 single nucleotide polymorphism (SNP) rs11322783 in patients with COVID-19 (n = 128), in comparison with a validated data set of European healthy controls (n = 14152)." (PMID 35208821, 2022). "In this study, we found different levels of total WBC and neutrophils among IFNL4 SNP genotypes; in particular, patients with COVID-19 homozygous for the IFNL4-producing allele were more represented in the group with low-counts of WBC and neutrophils." (PMID 35208821, 2022). "We also assessed sex and IFNL4 genotype during our analysis since both have been associated with COVID-19 disease outcomes." (PMID 36385011, 2022). "The IFNL4 producing ΔG/ΔG genotype has been associated with higher viral loads in patients with COVID-19, but its contribution remains controversial." (PMID 35208821, 2022). "We also assessed patient characteristics such as sex and the IFNL4 genotype, where both have been associated with more severe COVID-19 outcomes." (PMID 36385011, 2022). "Our findings suggest that, like other infectious diseases caused by RNA viruses, genetic variants of IFNL4 can predispose to COVID-19." (PMID 34707167, 2021). "To this end, we analyzed the rs12979860 polymorphism in IFNL4 in a cohort of COVID-19 patients and compared it with the general population without this disease." (PMID 34707167, 2021). "In summary, we have found that the IFNL4 rs12979860 polymorphism was associated with the presence of COVID-19 in a Spanish population." (PMID 34707167, 2021). "Analysis of IFNL4 genetic variants may provide useful information to evaluate the efficacy of these treatments in COVID-19." (PMID 34707167, 2021). "We propose that confirming our findings can help to understand some facts about COVID-19 that may be influenced by IFNL4 polymorphisms." (PMID 34707167, 2021). "With these antecedents, we investigated whether there was also a relationship of IFNL4 genetic variants with COVID-19." (PMID 34707167, 2021). "In this study, we investigated whether there was a relationship of the rs12979860 polymorphism of IFNL4 with COVID-19." (PMID 34707167, 2021). "We investigated the association of three substantial gene polymorphisms (FURIN, IFNL4, and TLR2) with COVID-19 disease susceptibility and severity to help predict prognosis." (PMID 38703289, 2024). "In conclusion, FURIN, IFNL4, and TLR2 gene variants are associated with the risk of COVID-19 occurrence and linked to increased severity and worse outcomes in Egyptian patients." (PMID 38703289, 2024). "The FURIN, IFNL4, and TLR2 genotypes and their alleles differed significantly between COVID-19 patients and controls, as well as between patients with severe or critical illness and those with a non-severe presentation." (PMID 38703289, 2024). "FURIN, IFNL4, and TLR2 gene variants are associated with the risk of COVID-19 occurrence as well as increased severity and poor outcomes in Egyptian patients." (PMID 38703289, 2024). "This clinical study involving 178 COVID-19 patients revealed that carriers of IFNL3 and IFNL4 minor alleles are less likely to progress from mild to moderate COVID-19, that is, to develop COVID-19-related pneumonia." (PMID 38288121, 2023). "Given the importance of the IFN response in the control of viral infections, IFN (IFNL1 and IFNL4) targeted therapies for COVID-19 are currently being developed." (PMID 38143441, 2023). "This systematic review and meta-analysis will summarize the association of IFNL4, ACE1, PKR, IFNG, MBL2 genetic polymorphisms, and severe COVID-19." (PMID 35623072, 2022). "The IFNL4 SNP was also analyzed according to the haematological and clinical parameters of patients with COVID-19." (PMID 35208821, 2022).
COVID-19 (continued). "Different levels of white blood cells (p = 0.036) and neutrophils (p = 0.042) were found in the IFNL4 different genotypes in patients with COVID-19; the ΔG/ΔG genotype was more represented in the groups with low white blood cells and neutrophils." (PMID 35208821, 2022). "Our results indicate that rs11322783 IFNL4 genotypes are similarly distributed between patients with COVID-19 and healthy controls." (PMID 35208821, 2022). "In conclusion, although patients with COVID-19 did not exhibit a different distribution of the IFNL4 SNP, the ΔG/ΔG genotype was associated with a lower count of immune cell populations." (PMID 35208821, 2022). "These variations in IFNL3 and IFNL4 may have an impact on the efficacy of these drugs in COVID-19 treatment." (PMID 34306260, 2021). "This is a study comparing a genetic variant of IFNL4 in a population of COVID-19 patients with the general population without this disease." (PMID 34707167, 2021). "However, rs8099917 is in relatively weak linkage disequilibrium with IFNL4 functional SNPs in European populations (such as Irish,) and the lack of association should be confirmed with other informative SNP e.g. rs368234815 before ruling out a role for IFNL4 in COVID-19 patients." (PMID 38953458, 2024). "In this regard, the frequency of the CC genotype was similar between the COVID-19 patients and a cohort of 309 patients with chronic hepatitis C in our hospital (37.85% vs. 34.60%, data not shown), suggesting a similar effect of IFNL4 polymorphisms in these diseases." (PMID 34707167, 2021). "We studied the relationship between FURIN, IFNL4, and TLR2 genotypes and laboratory parameters in COVID-19 patients, particularly ALT as a marker of liver injury." (PMID 38703289, 2024). "This study will systematically evaluate the impact of IFNL4, ACE1, PKR, IFNG, and MBL2 in the course of severe COVID-19 using electronic databases and paper-based literature with an eye to the current genetic profile of the severe COVID-19 population." (PMID 35623072, 2022). "This study aims to perform a systematic evaluation and meta-analysis of the effects of IFNL4, ACE1, PKR, IFNG, and MBL2 in the course of severe COVID-19." (PMID 35623072, 2022). "Our results suggest that the polymorphic status of IFNL3/IFNL4 does not affect the rate of infection, since the genotypes are fully in Hardy-Weinberg equilibrium, nor the likelihood of a severe outcome of COVID-19." (PMID 34249902, 2021). "Moreover, the IFNL4 SNP seems to not influence the clinical outcome of COVID-19 being not related to clinical severity (CALL score or ICU admission) and patients’ survival outcomes." (PMID 35208821, 2022). "However, it remains unclear whether IFNL4 can regulate neutrophil response and its impact on neutrophil functions and related IFN-III pathways in COVID-19 individuals." (PMID 35208821, 2022). "Thus, in order to provide insight into the impact of the IFNL4 SNPs in SARS-CoV-2 infections, we investigated whether genotypes of rs11322783 SNP were differently distributed between patients with COVID-19 and the European validated group of healthy controls." (PMID 35208821, 2022). "However, the effects of IFNL4, ACE1, PKR, IFNG, and MBL2 in severe COVID-19 have not been systematically assessed." (PMID 35623072, 2022).
chronic hepatitis C (10 papers, 2013 to 2021). "Single nucleotide polymorphisms (SNPs) within DNA region containing interferon lambda 3 (IFNL3) and IFNL4 genes are prognostic factors of treatment response in chronic hepatitis C (CHC)." (PMID 27125837, 2017). "This investigation aimed at validating the impact of IFNL3 rs4803217 and IFNL4 rs368234815 genotypes on hepatic IFNL3 mRNA expression in clinical samples in chronic hepatitis C in man." (PMID 26606750, 2015). "In this study, we compared the role of IFNL4 variants with IFNL3-(rs12979860) and IFNL3-(rs8099917) on response to pegylated (PEG)-IFN and Ribavirin (RBV) in patients with chronic hepatitis C GT2/3." (PMID 26699619, 2015). "Common single nucleotide polymorphisms (SNPs) in the IFNL3, IFNL4 and the IFNL receptor α-subunit genes have been strongly associated with IFN-α-based treatment of chronic hepatitis C virus infection." (PMID 26038748, 2014). "In conclusion, our data, obtained from a relatively broad panel of human liver tissue samples of various etiology, demonstrate exclusive induction of IFNL4 mRNA in livers of chronic hepatitis C patients, albeit only in a subgroup of them." (PMID 24376784, 2013). "In this broad range of samples, IFNL4 mRNA transcripts were exclusively detected in specimens from patients with chronic hepatitis C, albeit only in half of them." (PMID 24376784, 2013). "Another study showed that IFNL4-∆G genotype is associated with high levels of ISGs and that hepatic levels of ISG15 in chronic hepatitis C are strongly associated with IFN-λ4 expression, suggesting that IFN-λ4 contributes to induction of ISGs in HCV-infected liver." (PMID 26457705, 2015). "We have confirmed that the linkage disequilibrium between the IFNL4-∆G allele and IL28B SNP (rs8099917) is high and that the IFNL4-∆G allele is strongly associated with treatment failure of PEG-IFN and ribavirin therapy in patients with Japanese chronic hepatitis C." (PMID 24349500, 2013). "Samples were obtained from patients with a broad panel of disorders including no liver disease, liver diseases of non-viral etiology, chronic hepatitis B and chronic hepatitis C. Hepatic IFNL4 transcripts were detectable exclusively in a subgroup of chronic hepatitis C patients (24/45)." (PMID 24376784, 2013). "To better understand the dynamics between type I and III IFNs expression in chronic hepatitis C patients, we also quantified the expression of IFNA1, IFNL1, IFNL2, IFNL3 and IFNL4 in 24 healthy volunteers." (PMID 34307188, 2021). "Individuals with the ancestral IFNL4-dG allele are not able to clear HCV in the acute phase and have more than a 90% probability to develop chronic hepatitis C (CHC)." (PMID 34385466, 2021).
viral infections (10 papers, 2015 to 2023). "Moreover, as proof of the key role of IFN-III in the regulation of antiviral immunity, SNPs in IFNL4 loci were associated with clinical outcomes of different viral infections including those caused by SARS-CoV-2." (PMID 35208821, 2022). "Only the IFNL4 SNP ss469415590TT>ΔG (or rs3682134815) genotype distribution deviated from Hardy–Weinberg equilibrium, which is likely caused by the positive selection of the ss469415590TT allele favorable for humans fighting against viral infections." (PMID 30157968, 2018). "Furthermore, an association of the presence or absences of IFNL4 and other viral infections, including HBV, have still to be confirmed." (PMID 28862649, 2017). "The AUC-ROC was 0.881 for IFNL3 rs12979860, 0.748 for IFNL3 rs8099917, 0.726 for IFNL3 rs12980275, and 0.869 for IFNL4 rs368234815, suggesting that host genetic factors are generally important for the resolution of viral infection." (PMID 34775984, 2021). "The HCV UpA dinucleotide frequency was significantly associated with the IFNL4 SNP rs12979860 genotypes; interestingly, ribonuclease L (RNase-L), an ISG that cleaves viral RNA to control viral infections in animals, targets both UpA and UpU dinucleotides." (PMID 31478835, 2019). "The role of IFNL4 in infectious disease susceptibility in general and HIV-1, in particular, is a topic of great interest due to the potential shared roles in innate immunity against several viral infections." (PMID 35481423, 2022). "Later, it was identified that one of the SNPs, variant ss469415590, is forming a thus far unknown IFN, IFNL4, which is resulting in poor treatment outcome and little spontaneous clearance, indicating that the role of IFN in viral infections is more complex than originally anticipated." (PMID 28862649, 2017).
Cirrhosis (8 papers, 2016 to 2025). A chronic disorder of the liver in which liver tissue becomes scarred and is partially replaced by regenerative nodules and fibrotic tissue resulting in loss of liver function. "We also observed that host IFNL4 gene polymorphisms were associated with antibody responses as well as other factors such as sex and cirrhosis status of the patient." (PMID 41076628, 2025). "Moreover, the presence of the functional IFNL4 gene leads to reduced liver inflammation and is associated with protection against cirrhosis in HCV chronic carriers." (PMID 35481423, 2022). "Overall, our data indicate a clear impact of IFNL4 genotype on clinical outcome in patients with cirrhosis treated with a suboptimal DAA regimen, together with a clear association between IFNL4 genotypes and gene expression." (PMID 29534310, 2018). "We make a report of a time‐dependent molecular signature detectable in blood associated with IFNL4 genotypes, which, in itself, is associated with SVR in patients with cirrhosis." (PMID 29534310, 2018). "The variant rs12971396 in IFNL4 is in LD (r2 = 1.0 in East Asian populations) with another variant at the same locus (rs12979860) that has been strongly associated with chronic HCV infection, a main driver of both cirrhosis and HCC in East Asia." (PMID 40823170, 2025). "Based on these data, we hypothesized that host IFNL4 genotype might particularly affect viral outcome in patients with cirrhosis treated with the shortest protocol (16 weeks)." (PMID 29534310, 2018). "In univariate analyses lower liver enzymes and IP10 levels, female sex, IFNL4 CC genotype and the absence of cirrhosis were all associated with SVR." (PMID 27281344, 2016). "Sex, cirrhosis status, prior IFN-based treatment, log10 of baseline viral load, and IFNL4 haplotypes were included as covariates to minimize the possible confounding effects." (PMID 41076628, 2025). "More studies were identified for IFNL3/IFNL4 than any other gene, with seven original studies (with a total of 3,154 patients) and three meta‐analyses using HCC as an outcome and six using cirrhosis or fibrosis." (PMID 29397014, 2018). "These include host factors such as a younger age (<45 years), a lower BMI, the absence of advanced fibrosis/cirrhosis, a naïve treatment status and an IFNL4 CC genotype." (PMID 27281344, 2016). "To account for non-viral factors associated with SVR, we used logistic regression to test for association between treatment outcome and patient’s cirrhosis status, gender, baseline viral load, prior IFN-based treatment and IFNL4 SNP rs12979860 genotypes (CC vs non-CC) in a multivariate model." (PMID 34671027, 2021). "However, the SVR at 12 weeks (SVR12) rate in the 24‐week DAA only arm among patients with cirrhosis (where a clear IFNL4 effect was observed) was 79% in this study, comparable to the 80% response rate in the 16‐week arm among patients without cirrhosis (where no IFNL4 gene effect was observed)." (PMID 29534310, 2018). "Interestingly, in the absence of cirrhosis, we could not detect a significant impact of IFNL4 genotypes in the analyses performed (DAA therapy arms only)." (PMID 29534310, 2018).